FXN (frataxin)
Diseases named in the same sentence as FXN in open-access papers (continued):
Sharing a sentence is not in itself a finding about the gene and the disease.
tumor (15 papers, 2007 to 2025). "Frataxin missense mutations have indeed been identified in cancer tissues where tumor-initiating cells show a higher iron uptake." (PMID 35203634, 2022). "There have been scattered reports implying an association between frataxin and neoplastic disease." (PMID 19455237, 2007). "In H23 and H2030 cells, short hairpin RNAs (siRNAs) targeting Frataxin were utilized to investigate further its role in MRPS16‐mediated tumour cell proliferation, migration and invasion." (PMID 38506080, 2024). "The reduced Ki‐67 expression in xenograft tumours of Frataxin silencing groups also implied that Frataxin silencing had the capability to counteract the MRPS16 influence on promoting cell growth." (PMID 38506080, 2024). "Collectively, PI3K/AKT/Frataxin signalling axis activation by MRPS16 was indicated to enhance tumour growth." (PMID 38506080, 2024). "Collectively, MRPS16 enhances tumour development through PI3K/AKT/Frataxin signalling axis activation." (PMID 38506080, 2024). "In a next step, the authors investigated the potential tumor suppressing effect of enforced frataxin expression in the colon cancer lines MIP101, DLD2 and HT29, which lack endogenous expression of the protein." (PMID 19949549, 2009). "Moreover, MRPS16‐knockdown‐mediated Frataxin overexpression was shown to restore the reduction in tumour cells proliferation, migration and invasion." (PMID 38506080, 2024). "Mechanistically, MRPS16 may enhance tumour progression through PI3K/AKT/Frataxin signalling pathway activation." (PMID 38506080, 2024). "Hypoxia-induced stress in tumors is mediated by FXN, which may contribute to tumor cell survival and progression." (PMID 36338346, 2022). "The impairment of the frataxin function may damage mitochondria and also increase the chance of tumor formation." (PMID 35203634, 2022). "However, frataxin was also reported to induce mitochondrial oxidative metabolism in colon cancer cells, thereby suppressing tumor growth." (PMID 33287315, 2020). "Some works corroborate this assumption as an increase in the antioxidant response was found upon FXN overexpression in tumour cell lines, arguing that this protein could also act as a tumour suppressor." (PMID 33126466, 2020). "Frataxin has previously been shown to function as a tumor suppressor as its overexpression in a colon cancer model has been shown to decrease growth rates, inhibit soft agar colony formation, and prevent tumor growth in mice." (PMID 31366108, 2019). "The authors also reported impaired phosphorylation of the stress-inducible p38 MAP kinase and suggest that frataxin may, in fact, be a mitochondrial tumor suppressor protein." (PMID 20090835, 2010). "Thus, frataxin may function in an antioxidant capacity to enhance tumor survival and progression by sequestering excess iron, allowing for its utilization rather accumulation that could lead to increased oxidative distress." (PMID 31366108, 2019). "Several components of its biosynthetic pathway, including cysteine disulfurase (NFS1), frataxin (FTX), and glutathione, have been shown to foster tumor progression and resistance to therapies in different models." (PMID 33287315, 2020). "Our data not only indicated that MRPS16 activated the PI3K/AKT/Frataxin axis to facilitate tumour cell proliferation, migration and invasion but also that MRPS16 activated PI3K/AKT signalling, which promoted Frataxin protein expression and promoted LAUD progression." (PMID 38506080, 2024).
infection (10 papers, 2011 to 2025). The state of being infected such as from the introduction of a foreign agent such as serum, vaccine, antigenic substance or organism. "FXN mRNA expression levels, measured by qRT-PCR were high in the first week following infection and then fell by ~50% by week 12 compared with untreated cells." (PMID 27518705, 2016). "Long-term LV FXN gene transfer was demonstrated by the fact that vector copy numbers of both LVs remained constant post infection up to the 8-week time point investigated." (PMID 27518705, 2016). "We next measured FXN gene expression in pHR'SIN-cPPT-SFFV-FXN-WPRE-infected cells using quantitative real-time PCR (qRT-PCR) at 2, 8 and 12 weeks post infection compared with uninfected cells and control normal human and mouse fibroblasts to determine levels and longevity of gene expression." (PMID 27518705, 2016). "After normalizing to endogenous GAPDH gene expression, FXN expression in the human and mouse FRDA cells reached 96- and 210-fold, respectively, after infection, compared with uninfected FRDA cells 0.5- and 0.2-fold, respectively, compared with normal fibroblasts." (PMID 27518705, 2016).
mitochondrial disease (10 papers, 2015 to 2025). "Friedreich’s Ataxia (FRDA) is an autosomal recessive mitochondrial disease that is caused by a mutant Frataxin (FXN) gene." (PMID 40757576, 2025). "However, based on the knowledge of a mitochondrial role of frataxin it could be tempting to hypothesize a possible contribution of the relative frataxin deficiency in heterozygotes, to the severity of their mitochondrial disease." (PMID 26338206, 2015). "It has been proposed that SDHIs may be harmful to patients with mitochondrial diseases since two SDHBIs, bixafen and fluxapyroxad, were shown to cause apoptosis in cells from patients with Friedrich ataxia, a mitochondrial disease caused by mutations in the frataxin gene." (PMID 38540197, 2024). "Nqo15 is a subunit of respiratory complex I of the bacterium Thermus thermophilus, with strong structural similarity to human frataxin (FXN), a protein involved in the mitochondrial disease Friedreich’s ataxia (FRDA)." (PMID 38339189, 2024). "FRDA is a mitochondrial disease, as the deficient protein in FRDA (frataxin) is crucial for mitochondrial iron-sulfur cluster containing enzymes involved in oxidative phosphorylation and the Krebs cycle." (PMID 26755195, 2016). "In 2 mitochondrial disease models, hypoxia corrects defects that arise as a consequence of the genetic lesion—decreasing excessive molecular oxygen in the setting of a defective ETC in Ndufs4 knockout and restoring iron sulfur cluster levels in frataxin knockout." (PMID 37220109, 2023). "Finally, our finding of an extra-mitochondrial form of frataxin raises the possibility that FA might not be simply a mitochondrial disease and that decreased extra-mitochondrial frataxin could contribute to disease etiology." (PMID 30451920, 2018).
cardiac disease (7 papers, 2008 to 2024). "The heart disease of Friedreich’s Ataxia (FRDA) results from inherited deficiency of frataxin (FXN), a mitochondrial protein important in energy homeostasis." (PMID 28542596, 2017). "For example, some “partial function” variants may share a preserved part of frataxin that contributes to milder neurologic or cardiac disease but on the other hand, may more severely impair a different frataxin component that is more critical in the visual and/or pancreatic tissues." (PMID 38396238, 2024). "This study is the first to document the progression of lysine-acetylated proteins and demonstrate a correlation between acetylation and cardiac function in the heart of the conditional FXN KO mouse model of FRDA heart disease." (PMID 28542596, 2017). "We previously demonstrated that acetylation in the conditional FXN KO heart is dramatically increased in late stages of heart disease and that the majority of protein acetylation was localized to mitochondria." (PMID 28542596, 2017). "The conditional FXN KO model thereby acts as a “stressed heart” model to examine the role of acetylation in heart disease and failure." (PMID 28542596, 2017). "In the homozygous group, the number of GAA repeats in the shorter allele of the FXN gene (GAA1) is inversely related to cellular levels of frataxin, and there has therefore been interest in the ability of GAA1 to explain cardiac disease severity in FRDA." (PMID 38814901, 2024). "Many cardiac diseases with abnormal metabolism and energy homeostasis are liable to result in impaired SIRT3 activity in a manner similar to the FXN KO model, leading to abnormal mitochondrial protein acetylation in the heart and impaired cardiac function." (PMID 28542596, 2017). "Idebenone, an antioxidant used as therapeutic agent in FRDA has shown to delay the cardiac disease onset, demonstrating that it is cardioprotective, even when there is a complete lack of frataxin." (PMID 21687738, 2011).
autosomal recessive disease (5 papers, 2019 to 2026). Autosomal recessive form of disease. "Friedreich's ataxia (FRDA) is a multisystem, autosomal recessive disease caused by biallelic expansion of GAA repeats in intron 1 of the frataxin gene (FXN)." (PMID 41865460, 2026). "It is a rare hereditary autosomal recessive disease caused by mutations in the frataxin (FXN) gene resulting in decreased levels of functional frataxin protein." (PMID 37889470, 2024).
movement disorder (3 papers, 2020 to 2026). Neurological conditions resulting in abnormal voluntary or involuntary movement, which may impact the speed, fluency, quality and ease of movement. "Notwithstanding, our results are consistent with the knowledge that FXN deficiency causes movement disorder in FA." (PMID 36658420, 2023).
myopathy (3 papers, 2017 to 2022). A disease of the muscle in which the muscle fibers do not function properly. "Daily exercise was shown to delay myopathy progression in the FXN knockin knockout (KIKO) mouse model of FRDA." (PMID 35531957, 2022).
iron metabolism disorders (2 papers, 2015 to 2021). "Consistent with the mitochondrial localization of frataxin, changes in expression and/or deficiency of this protein are associated with mitochondrial dysfunction and iron metabolism disorders." (PMID 26517126, 2015).
FXN also shares sentences with these, for which no sentence is quoted: fragile X syndrome (7 papers); ataxia telangiectasia (5); myotonic dystrophy type 1 (5); cerebellar ataxia (4); Genetic neurodegenerative disease (4); scoliosis (4); Limb ataxia (3); amyotrophic lateral sclerosis (2); dentatorubral-pallidoluysian atrophy (2); developmental delay (2); diabetes Mellitus type 2 (2); Hepatic steatosis (2); hepatocellular carcinoma (2); hereditary neurodegenerative disease (2); mastitis (2); migraine (2); Parkinson (2); protein deficiency (2); Spastic paraplegia (2); spinocerebellar ataxia type 1 (2); Stroke (2); acute cystitis (1); Alzheimer disease (1); attention deficit-hyperactivity disorder (1); autism (1); axonal neuropathy (1); Baratela-Scott syndrome (1); Barth syndrome (1); bladder cancer (1); Cerebral ischemia (1).
A further 62 diseases each share a sentence with FXN in 1 paper.